VWF (von Willebrand factor)
Diseases named in the same sentence as VWF in open-access papers (continued):
Sharing a sentence is not in itself a finding about the gene and the disease.
mastitis (1 paper, 2022). Inflammation of breast tissue during lactation or postpartum due to an obstructed duct or infection. "We found that the cflA, fnbA, ebpS, spa, sdrC, coa, emp, vWF, atl, sasH, sasA, and sasF adhesion genes, as well as the aur, hglA, hglB, and hglC toxin genes were highly associated in clinical mastitis strains." (PMID 36419431, 2022). "These genes were associated with the cflA, fnbA, ebpS, spa, sdrC, coa, emp, vWF, atl, sasH, sasA and sasF adhesin genes in clinical mastitis isolates." (PMID 36419431, 2022). "Our findings suggest that the cflA, fnbA, ebpS, spa, sdrC, coa, emp, vWF, atl, sasH, sasA and sasF adhesion genes, as well the aur, hglA, hglB, and hglC toxin genes are associated with clinical mastitis, and thus could be useful for screening tests and as candidates for more effectives vaccines." (PMID 36419431, 2022).
mastocytosis (1 paper, 2015). A clonal myeloproliferative neoplasm characterized by the proliferation and accumulation of neoplastic mast cells in one or multiple organs or organ systems. "The spectrum of mastocytosis-related clotting disorders includes acquired vWF disease, acquired disorders of the coagulation cascade, and probably of fibrinolysis." (PMID 26447996, 2015).
melancholic depression (1 paper, 2016). "No mediation was found for IGFBP1, ACE and B2M (comparison atypical and melancholic depression) and B2M, ANG2 and VWF (comparison atypical depression and controls)." (PMID 27404283, 2016).
memory impairment (1 paper, 2022). "The higher serum Cathepsin D, IgE, EGFR, MMP-9, vWF, haptoglobin, and p-Tau181 levels were associated with severity of memory impairment (as indicated by lower MMSE and MoCA scores, and higher ADL, CDRglobal, and CDRsob scores)." (PMID 35769604, 2022).
metastatic cancer (1 paper, 2021). A carcinoma which has spread from the original site of growth to another anatomic site. "While ADAM28 acts as a semi-functional homologue of ADAMTS-13 in cleaving circulating VWF, it is interesting to note that while ADAMTS-13 levels have been shown to decrease in a range of metastatic cancer including breast, ADAM28 expression is correlated with advanced disseminated disease." (PMID 33571850, 2021).
metastatic melanoma (1 paper, 2024). A melanoma that has spread from its primary site to another anatomic site. "The hazard ratios in the group with metastatic melanoma (n = 8) were non-significant with 1.004 for factor VIII:C (p: 0.3495) and 1.005 for vWF ag (p: 0.1840)." (PMID 39487855, 2024).
microsporidia infection (1 paper, 2021). "Another potential manner by which VWF may enhance systemic spread of microsporidia infection is by enhancing its ability to infect host cells." (PMID 34095003, 2021).
mucosal (1 paper, 2022). "Blood tests to identify von Willebrand factor activity, fibrinogen, factor VIII, or von Willebrand factor antigen were required in 10 cases where bleeding (mucosal hemorrhage or low hemoglobin) was detected." (PMID 36381689, 2022).
multiple epiphyseal dysplasia (1 paper, 2008). Multiple epiphyseal dysplasias (MED/EDMs) are characterized by epiphyseal anomalies causing joint pain early in life, recurrent osteochondritis and early arthrosis. "Mutations in the vWF A domain of matrilin-3 cause multiple epiphyseal dysplasia (MED), however the pathological mechanism remains to be determined." (PMID 18518980, 2008).
murine typhus (1 paper, 2012). "The activation pattern in murine typhus patients followed a distinct ‘endothelial perturbation profile’, with prominent increases in the levels of endothelium-derived factors, including VWF, sTM, tPA, and PAI-1." (PMID 22192733, 2012). "Plasma concentrations of sTM and VWF were elevated in both typhus groups as compared with controls, but the increases were significantly more prominent in patients with murine typhus (p <0.001 for both indices)." (PMID 22192733, 2012).
myocardial disease (1 paper, 2021). "Currently, there is limited information regarding the contribution of endocardial vWF to thrombosis in cats with myocardial disease." (PMID 33925795, 2021). "The aim of this study was to investigate the expression of vWF in the LA of cats at different clinical stages of myocardial disease." (PMID 33925795, 2021). "Importantly, our finding in cats with advanced myocardial disease are similar to two human studies where patients with hemodynamical disturbance in the LA secondary to various cardiac causes showed elevated endocardial vWF compared to the non-cardiac patients using immunohistological microscopy." (PMID 33925795, 2021).
nephrotic syndrome (1 paper, 2021). A collection of symptoms that include severe edema, proteinuria, and hypoalbuminemia; it is indicative of renal dysfunction. "Nephrotic syndrome can cause a plasma soluble thrombomodulin, and von Willebrand factor levels that can contribute to the development of TMA." (PMID 34646728, 2021).
neuropathy (1 paper, 2024). A disorder affecting the nervous system that manifests with pain, tingling, numbness, and/or muscle weakness. "In this previous study, we performed immunohistochemical analysis of skin biopsies at the distal calf and found that IENF density was severely depleted in neuropathy groups but that vWF-positive blood vessels were significantly increased in the painful-DPN group." (PMID 39512388, 2024). "Additionally, vWF immunoreactivity also positively correlated with neuropathy measures including the clinical scoring systems (TCNS and NIS-LL), objective measures (nerve conduction studies and QST measures), and the composite score NIS-LL + 7 (Spearman's correlation, r = 0.641, p < 0.001)." (PMID 39512388, 2024). "Importantly, the increase in vWF was significantly greater in the painful- compared with the painless-DPN group, despite both groups having a similar severity of neuropathy." (PMID 39512388, 2024).
Noonan syndrome (1 paper, 2025). Noonan Syndrome (NS) is characterized by short stature, typical facial dysmorphism and congenital heart defects. "It is known that 50% of individuals with Noonan syndrome exhibit platelet dysfunction, and in addition to this, deficiencies in coagulation factors, such as factor VIII (von Willebrand factor), are also commonly identified." (PMID 39860591, 2025).
Oral leukoplakia (1 paper, 2023). A thickened white patch on the oral mucosa that cannot be rubbed off. "The protein expression of von Willebrand factor and NG2 was assessed in oral leukoplakia (i.e., oral potentially malignant disorders) and OSCC samples." (PMID 37015965, 2023).
orthostatic hypotension (1 paper, 2022). Sudden fall of the blood pressure of at least 20/10 mm Hg when a person stands up. "A previous study has similarly found that patients with syncope and orthostatic hypotension have increased levels of vWF during orthostasis." (PMID 36414707, 2022).
osteoporosis (1 paper, 2023). A condition of reduced bone mass, with decreased cortical thickness and a decrease in the number and size of the trabeculae of cancellous bone (but normal chemical composition), resulting in increased fracture incidence. "Some scholars have found that long-term deficiency of FVIII is an independent risk factor for osteoporosis and proposed that the mechanism may be FVIII:vWF complex inhibits osteoclast production and differentiation through the RANKL-OPG pathway." (PMID 37592270, 2023).
ovarian angiosarcoma (1 paper, 2014). A malignant vascular neoplasm arising from the ovary. "Because of the rarity and morphologic heterogeneity of ovarian angiosarcoma, immunopositivity with a specific endothelial marker (CD31 or von Willebrand factor) is a diagnostic prerequisite." (PMID 24520828, 2014).
ovarian serous tumor (1 paper, 2008). A benign, borderline, or malignant epithelial tumor of the ovary characterized by the presence of neoplastic epithelial cells that, in well differentiated tumors, resemble the epithelial cells of the fallopian tube and, in poorly differentiated tumors, show anaplastic features. "Interestingly, EMILIN2 has been found to play a role in trophoblast invasion of the uterine wall and is enriched at the level of mRNA expression in ovarian serous tumors, and Von Willebrand factor has been associated with multiple cancers." (PMID 18652693, 2008).
panhypopituitarism (1 paper, 2024). Insufficient production of all the anterior pituitary hormones. "Deficiencies of factor V, VIII, and VWF have been reported in a patient with panhypopituitarism." (PMID 39006713, 2024).
pelvic inflammatory disease (1 paper, 2020). Pelvic inflammatory disease (PID) is an acute or chronic inflammation in the pelvic cavity. "The key target proteins for the SC and PS against pelvic inflammatory disease with dampness-heat stasis syndrome included vascular endothelial growth factor A (VEGFA), von willebrand factor (VWF), interleukin 6 (IL6), tumor necrosis factor (TNF) and nuclear transcription factor 1 (NFκB1)." (PMID 33424592, 2020).
pemphigus vulgaris (1 paper, 2024). Pemphigus is a group of chronic autoimmune skin diseases characterized by blister formations on the outer layer of the skin and the mucous membranes. "Among these genes, FGA, VWF, and ACTG1 were abnormally expressed, supporting the hypothesis that platelet activation may play an important role in the progression of pemphigus vulgaris." (PMID 39593117, 2024). "The dysregulation of genes such as FGA, VWF, and ACTG1 suggests that alterations in their transcription and expression may contribute to the pathogenesis of pemphigus vulgaris." (PMID 39593117, 2024).
Peri-Implantitis (1 paper, 2019). An inflammatory process with loss of supporting bone in the tissues surrounding functioning DENTAL IMPLANTS. "Positive staining for VWF was observed in peri-implantitis affected tissue (yellow arrows) and in control (black arrows)." (PMID 31242601, 2019).
pericardial tamponade (1 paper, 2017). "A vWF:ratio < 0.7 at VAD start or end of surgery was found to be a risk factor in LVAD patients correlating to higher incidences of pericardial tamponade and re-operation." (PMID 28234916, 2017). "Intraoperative vWF:ratios <0.7 correlate with higher incidences of pericardial tamponade and re-operation." (PMID 28234916, 2017). "But we found a correlation between the vWF:ratio < 0.6 at early perioperative time points (VAD-start and end of surgery) with the incidence of postoperative pericardial tamponade with required re-operation." (PMID 28234916, 2017). "We detected a correlation between vWF:ratio <0.7at LVAD-start (r = -0.583, p = 0.006) or at the end of surgery (r = -0.461, p = 0.035) and the occurrence of pericardial tamponade." (PMID 28234916, 2017).
pituitary adenoma (1 paper, 2025). "It was found that a prolactin-secreting pituitary adenoma was associated with TMA (confirmed as von Willebrand factor-positive microthrombi in the arterioles and capillaries of several organs, primarily the heart and brain)." (PMID 40217615, 2025).
placenta previa (1 paper, 2023). "Similar study may be considered to explore the vWF levels and placenta previa in the further study." (PMID 36743690, 2023).
Pleural effusion (1 paper, 2012). The presence of an excessive amount of fluid in the pleural cavity. "Moreover, VWF propeptide levels correlated better with markers of disease severity (platelet count, liver enzymes, serum albumin and pleural effusion index) than corresponding VWF levels." (PMID 22563509, 2012).
Portal vein thrombosis (1 paper, 2020). Thrombosis of the portal vein and/or its tributaries, which include the splenic vein and the superior and inferior mesenteric veins. "Although high VWF/FVIII may be risk factors for portal vein thrombosis (PVT) in patients with advanced chronic liver disease (ACLD), the impact of BT on PVT is unknown." (PMID 32052552, 2020).
postpartum hemorrhage (1 paper, 2016). Hemorrhage defined as a blood loss in excess of 500 mL after vaginal delivery or more than 1000 mL after a cesarean delivery. "Women with VWD appear to be at increased risk of experiencing postpartum hemorrhage (PPH), though the levels of VWF increase during pregnancy." (PMID 27780267, 2016).
primary hypertension (1 paper, 2019). "To examine the effects of SKA-31, we conducted experiments using the SHR model, which shares features of primary hypertension observed in various animal species and in humans such as elevated BP, thickening of the media of sMAs, and impaired endothelial function revealed by higher levels of vWF." (PMID 31450834, 2019).
primary hypogonadism (1 paper, 2021). "Other factors that were derived from the univariate analysis—such as age, depressive symptoms, von Willebrand factor, presence of primary hypogonadism, c-PWV, and having received chemotherapy for TC—did not significantly contribute to the model." (PMID 34830829, 2021).
pseudoexfoliation syndrome (1 paper, 2012). "The aim of the study was the assessment of the von Willebrand antigen (vWF Ag), E-selectin, and P-selectin concentration in blood plasma of patients with pseudoexfoliation syndrome (PEX)." (PMID 22593709, 2012).
pulmonary valve stenosis (1 paper, 2021). The pathologic narrowing of the orifice of the pulmonary valve. "Acquired cases of von Willebrand syndrome have been described and the destruction of the von Willebrand factor could explain bleeding in some NS patients with pulmonary valve stenosis." (PMID 34857025, 2021).
radiation fibrosis (1 paper, 2013). "PTX alone or in combination with tocotrienols did not alter cardiac radiation fibrosis, left ventricular protein expression of the endothelial markers von Willebrand factor and neuregulin-1, or phosphorylation of the signal mediators Akt, Erk1/2, or PKCα." (PMID 23894340, 2013).
respiratory distress syndrome (1 paper, 2020). "In one study, infants with respiratory distress syndrome and PH revealed well-preserved expression of caveolin-1, PECAM-1, and von Willebrand factor (vWF), indicating that there was no disruption of the endothelial layer." (PMID 32824651, 2020).
respiratory infections (1 paper, 2024). "An increase in plasma VWF associated with a decrease in ADAMTS-13 has been reported in respiratory infections of both viral and bacterial etiology." (PMID 39408067, 2024).
Salmonella Infections (1 paper, 2021). Infections with bacteria of the genus SALMONELLA. "The inflammatory trigger (salmonella infection) probably caused an upregulation of endothelial VWF secretion and increase of VWF plasma levels, which caused acute flare of the disease in analogy to triggering acute TTP by shiga toxin in an ADAMTS13 deficient mouse model." (PMID 33732721, 2021).
schwannoma (1 paper, 2020). A benign, usually encapsulated slow growing tumor composed of Schwann cells. "We found that upregulated genes PIK3CG, CSF1R, SPP1, and CCND1 and downregulated genes EGFR and VWF were significantly enriched in PI3K-Akt signaling pathway involved in VSs development, which can increase schwannoma cell proliferation, survival, and cell-matrix adhesion acting." (PMID 32733557, 2020).
Seizure (1 paper, 2019). A seizure is an intermittent abnormality of nervous system physiology characterized by a transient occurrence of signs and/or symptoms due to abnormal excessive or synchronous neuronal activity in the brain. "We measured serum copeptin and VWF parameters, including analyses of VWF:Antigen (WVF:Ag), VWF:collagen binding activity (VWF:CB) and VWF multimers in children with FS, febrile infections without seizures and additionally, in a non-febrile control group." (PMID 30605489, 2019).
skin atrophy (1 paper, 2026). The degeneration and thinning of the epidermis and dermis. "Diabetic rats showed skin atrophy, collagen damage, elevated ALDO levels, reduced MR and HSD11β2 expression, and increased vascular permeability, along with upregulation of VEGF and vWF." (PMID 41511372, 2026).
Skin rash (1 paper, 2023). A red eruption of the skin. "We found that skin involvement at specific focal points (i.e., a joint-related skin rash) had a 46% increased odds of higher vWF:Ag levels (p = 0.013), generalized skin involvement had 158% increased odds (p = 0.006), and eyelid peripheral blood vessel dilation had 32% increased odds (p = 0.036)." (PMID 36831088, 2023).
Sleep apnea (1 paper, 2023). An intermittent cessation of airflow at the mouth and nose during sleep is known as sleep apnea. "Plasma vWF, tau, and p-tau were associated with subjective sleep symptoms and sleep-disordered breathing outcomes (e.g., apnea index, oxygen saturation)." (PMID 37095856, 2023).
squamous carcinoma (1 paper, 2018). "High levels of OPG and low levels of vWF were significantly associated with both better progression free survival and overall survival in squamous carcinoma." (PMID 30005623, 2018). "Finally, levels of OPG and vWF were significantly associated with progression free and overall survival in squamous carcinoma." (PMID 30005623, 2018).
staphylococcal infection (1 paper, 2021). An infection caused by Staphylococcus. "SD-IVM further helped to demonstrate that during staphylococcal infection, when bacteria are caught, platelets start to adhere to Kupffer cells, and help clearing bacteria through their von Willebrand factor (vWF) and fibrinogen receptors GPIb and integrin αIIbβ3, respectively." (PMID 33644061, 2021).
Telangiectasia (1 paper, 2011). Telangiectasias refer to small dilated blood vessels located near the surface of the skin or mucous membranes, measuring between 0.5 and 1 millimeter in diameter. "In a case controle study, Veyradier and colleagues showed variable selective loss of the largest multimeric forms of von Willebrand factor in eight out of nine patients with bleeding digestive angiodysplasias or telangiectasias." (PMID 22294975, 2011). "Hence, VWF is more important than other clotting factors for hemostasis in abnormal vessels such as angiodysplasia and telangiectasia." (PMID 22294975, 2011).
testicular cancer (1 paper, 2015). A primary or metastatic malignant neoplasm that affects the testis. "The increases in plasma GDF-15 levels in testicular cancer patients during chemotherapy and its association with vWF and hsCRP suggest that GDF-15 is a potentially useful biomarker related to endothelial damage." (PMID 25590623, 2015). "Plasma levels of GDF-15 (pg/mL), vWF (%) and hsCRP (mg/L) in testicular cancer patients (n = 41) before, during and after completion of bleomycin- and cisplatin-based chemotherapy." (PMID 25590623, 2015). "However, its role in endothelial damage is supported by the fact that GDF-15 levels correlated with proteins known to reflect chemotherapy-related endothelial damage in testicular cancer patients, vWF and hsCRP." (PMID 25590623, 2015). "Furthermore, we showed that BEP-chemotherapy (Bleomycin; Etoposide; Cisplatin) did indeed affect plasma GDF-15 protein levels in testicular cancer patients and that these levels related to known endothelial damage biomarkers such as vWF and hsCRP." (PMID 25590623, 2015). "Protein levels of a candidate biomarker were measured in testicular cancer patient plasma before, during and after bleomycin-etoposide-cisplatin chemotherapy, and related to endothelial damage biomarkers (von Willebrand Factor (vWF), high-sensitivity C-Reactive Protein (hsCRP))." (PMID 25590623, 2015). "Based on data from the literature we selected GDF-15 for further validation on the protein level in plasma of testicular cancer patient during and after treatment, and related GDF-15 levels to known plasma endothelial damage biomarkers (vWF, hsCRP)." (PMID 25590623, 2015).
thymoma (1 paper, 2023). A neoplasm arising from the epithelial cells of the thymus. "This study showed that serum VWF levels in thymoma patients were higher than in healthy controls." (PMID 36991043, 2023).